Y_RNA (Y RNA )
Gene: Miscellaneous RNA gene on chromosome 21 (17,527,140 to 17,527,247, reverse strand). Ensembl gene ENSG00000200754.
Homologues: Orthologues: chimpanzee Y_RNA (96% identical), macaque Y_RNA (93% identical). Paralogues in human: Y_RNA (84% identical), RNY1P5 (83% identical), Y_RNA (83% identical), RNY1P1 (82% identical), Y_RNA (82% identical), Y_RNA (81% identical), Y_RNA (80% identical), Y_RNA (79% identical), RNY1 (78% identical), RNY1P11 (78% identical), Y_RNA (78% identical), RNY1P6 (77% identical), and 93 more.